TNFSF10 (TNF superfamily member 10)
Description:
Cytokine that binds to TNFRSF10A/TRAILR1, TNFRSF10B/TRAILR2, TNFRSF10C/TRAILR3, TNFRSF10D/TRAILR4 and possibly also to TNFRSF11B/OPG. Induces apoptosis. Its activity may be modulated by binding to the decoy receptors TNFRSF10C/TRAILR3, TNFRSF10D/TRAILR4 and TNFRSF11B/OPG that cannot induce apoptosis.
Synonyms: Apo-2L; CD253; APO2L; TRAIL; TL2; TANCR; TNLG6A
Tractability: Small molecule: it has a binding pocket of medium quality; it belongs to a druggable protein family. Antibody: UniProt places it where antibodies can reach, with high confidence; its Gene Ontology location is reachable by antibodies, with high confidence; UniProt predicts a signal peptide or a membrane-spanning region. PROTAC: ubiquitination databases record sites on it; a small molecule that binds it is known.
Target class: Secreted protein
Chemical probes: ML100
Gene: Protein-coding gene on chromosome 3 (172,505,508 to 172,523,476, reverse strand). Ensembl gene ENSG00000121858.
Subcellular location: Cell membrane; Secreted
Pathways (Reactome):
Programmed Cell Death: CASP8 activity is inhibited; Caspase activation via Death Receptors in the presence of ligand; Dimerization of procaspase-8; RIPK1-mediated regulated necrosis; Regulation by c-FLIP
Signal Transduction: TRAIL signaling
Gene Ontology:
Molecular function: cytokine activity; identical protein binding; protein binding; zinc ion binding; signaling receptor binding; TRAIL binding; tumor necrosis factor receptor binding; tumor necrosis factor receptor superfamily binding
Biological process: positive regulation of apoptotic process; positive regulation of canonical NF-kappaB signal transduction; positive regulation of extrinsic apoptotic signaling pathway; positive regulation of release of cytochrome c from mitochondria; TRAIL-activated apoptotic signaling pathway; apoptotic process; cell surface receptor signaling pathway; cell-cell signaling; signal transduction; cell communication; immune response; signaling
Cellular component: extracellular exosome; extracellular region; plasma membrane; membrane
Genetic constraint (gnomAD): Loss-of-function variants: 13 observed, 25.61 expected, observed/expected ratio (o/e) 0.51, 90% interval 0.33 to 0.81. The upper end of that interval is the gene's LOEUF score, 0.81, which puts it in group 3 of 6, group 1 being the genes least tolerant of losing a copy. Missense variants: 318 observed, 323.45 expected, observed/expected ratio (o/e) 0.98, 90% interval 0.9 to 1.08. Synonymous variants: 105 observed, 111.69 expected, observed/expected ratio (o/e) 0.94, 90% interval 0.8 to 1.11.
Homologues: Orthologues: chimpanzee TNFSF10 (99% identical), macaque TNFSF10 (96% identical), dog TNFSF10 (79% identical), rabbit TNFSF10 (78% identical), guinea pig TNFSF10 (72% identical), mouse Tnfsf10 (64% identical), tropical clawed frog tnfsf10 (47% identical), zebrafish tnfsf10 (43% identical). Paralogues in human: TNFSF11 (26% identical), CD40LG (20% identical), TNFSF15 (19% identical), FASLG (18% identical), TNFSF14 (17% identical), LTB (16% identical), TNF (14% identical), LTA (13% identical).
Diseases named in the same sentence as TNFSF10 in open-access papers:
TNFSF10 is named in the same sentence as 488 diseases in open-access papers, as found by Europe PMC text mining. Sharing a sentence is not in itself a finding about the gene and the disease. The quoted sentences say what the papers report.
breast carcinoma (328 papers, 2003 to 2026). "Lastly, in a syngeneic mouse model of breast cancer, TNFSF10-deficiency in breast tumors decreased tumor-infiltrated CD4+ and CD8+ T cell quantities." (PMID 35930348, 2023). "TNFSF10 has an inhibitory function in regulating breast cancer cell metastasis, but it has been reported that TNFSF10 can enhance the invasion of PDAC cells in vitro and increase the distant metastasis of pancreatic tumors in vivo." (PMID 38685045, 2024). "For instance, TNFSF10-deficiency in breast tumors has been linked to decreased tumor-infiltrating CD4+ and CD8+ T cells in a mouse model of breast cancer." (PMID 38535990, 2024). "In breast cancer (BC), RNAseq revealed increased expression of transcripts encoding immune regulatory receptors (CD200R1), pro-apoptotic molecules (TNFSF10), and pro-angiogenic factors (HGF and ANGPT1) in BC patients compared to healthy donors." (PMID 36733385, 2022). "TNFRSF10A, the receptor for the cytotoxic ligand TNFSF10/TRAIL, can regulate apoptosis mediated by TRAIL; and inactivating mutations has been demonstrated to play a role in metastasis of breast cancer." (PMID 35159257, 2022). "NCEH1 (along with RARRES3, NTN4, CFB, and CYP4ZJ) are frequently co-expressed with TNF superfamily member 10 (TNFSF10 also known as TRAIL) in breast cancer patients." (PMID 34281263, 2021). "Alteration of TNFSF10 and its mutually co-expressed genes are also investigated in clinical breast cancer patients, however, both upregulated and downregulated expression of those genes were detected." (PMID 28827731, 2017). "Association between the identified TRAIL/TNFSF10 SNPs and CD8+ lymphocyte apoptosis as well as with clinical radiosensitivity endpoints was studied in a set of 113 genotyped breast cancer patients, included in the Co-Ho-RT study." (PMID 26982083, 2016). "Collectively, our results suggested that TNFSF10 plays an important role in the regulation of antiviral immune responses in TNBC, and the expression is in part regulated by a genetic variant associated with breast cancer in Black women." (PMID 35930348, 2023). "Moreover, expression of top five genes (NCEH1, RARRES3, NTN4, CFB and CYP4Z1) that are frequently co-expressed with TNFSF10 in breast cancer patients, have been detected upon transfection with miR-7641 mimic." (PMID 28827731, 2017). "Interestingly, siRNA and shRNA-mediated knockdown of FYCO1 also sensitized resistant T47D breast carcinoma cells to TNFSF10/TRAIL-induced caspase activation and cell loss, suggesting that FYCO1 neutralization can also sensitize primarily resistant cells to the death ligand." (PMID 37418591, 2023). "TNFSF10, -13 and -13B were upregulated whereas TNFSF2, -12, -14, and TANK were unaffected in breast cancer compared to normal adjacent breast tissue." (PMID 35432372, 2022). "Our data confirmed RPS16 and TNFSF10 as two direct targets of miR-7641, while gene expression study showed that a group of genes are also deregulated by miR-7641, including many ribosomal proteins that are frequently co-expressed with RPS16 in breast cancer." (PMID 28827731, 2017). "Similarly, miR-7641 inhibition in MDA-MB-231 breast cancer cells upregulated RPS16, TNFSF10, MSRB3, CDNF, ZNF616, and NBEA, downregulated CUL3, and showed no remarkable changes for PIGC and the other genes." (PMID 28827731, 2017). "Our findings that IRF1 expression contributes to the regulation of RARRES3, GBP4, and CTSS, but not to the regulation of TNFSF10, are further validated by mRNA expression data from breast cancer patients." (PMID 29192143, 2017).
colon carcinoma (259 papers, 2003 to 2025). "We found enhanced expression of TNFSF10 in inflamed colonic tumors in the context of MDR1A deficiency, associated with accumulation of phosphorylated histone H2A.X and phosphorylated histone H3, as evidence of enhanced DNA damage and cell death." (PMID 28686677, 2017). "qPCR showed that all the tested proinflammatory mRNAs except TNFSF10 mRNA were expressed much lower than that of TTP in the colon cancer cells." (PMID 37705049, 2023). "LPS also increased COX2, CXCL1, ELK1, ICAM1, TNFSF10 and ZFAND5 but decreased BCL2L1, CYP19A1 and E2F1 mRNA levels in the colon cancer cells." (PMID 37705049, 2023). "Except TNFSF10 mRNA, all the other proinflammatory mRNAs were expressed much lower than that of TTP and VEGF mRNA was almost undetectable in the colon cancer cells." (PMID 33723275, 2021). "LPS increased COX2 and TNFSF10 mRNA levels but did not exhibit significant effect on HuA, LEPTIN and TNF mRNA levels in the human colon cancer cells." (PMID 37705049, 2023).
prostate carcinoma (240 papers, 2003 to 2026). A carcinoma that arises from epithelial cells of the prostate gland. "TNFSF10 has been reported to induce autophagy in some cancer cells, including prostate cancer, lung cancer, bladder cancer and other cancer cells." (PMID 36959587, 2023). "To understand the mechanism underlying the apoptosis induced by ANO1 inhibition, we performed the gene profiling analysis in prostate cancer PC-3 cells and found that ANO1 downregulation caused an increased expression of death receptor signaling molecules, such as TNF-α, TNFSF10 (TRAIL), and CASP7." (PMID 29899325, 2018). "As one of the genes significantly upregulated by miR-145 overexpression is the pro-apoptotic TNFSF10 gene, modulation of miR-145 may be an important therapeutic approach for the management of prostate cancer." (PMID 20588276, 2010). "Interestingly, TNFSF10 was also downregulated and TNFRSF10B (DR5) was increased in AT2R-mediated apoptosis in prostate cancer cells in our previous study." (PMID 28599664, 2017). "RNA microarray analyses of PC-3 cells overexpressing miR-145 indicated that TNFSF10 (TNF-related apoptosis-inducing ligand TRAIL) was significantly up-regulated and might be an important target of miR-145 in prostate cancer." (PMID 25322458, 2014). "Further MR analyses of these positive results indicated that G_Ruminococcaceae UCG014/TNFSF10 axis, G_Anaerofilum/TNFRSF14 axis, G_Erysipelotrichaceae UCG003/TNFSF10 axis, and P_Proteobacteria/cholesterol axis were key signaling pathways involved in the progression of prostate cancer." (PMID 39882449, 2024). "Notably, G_Ruminococcaceae UCG014/TNFSF10 axis and G_Anaerofilum/TNFRSF14 axis were found to act as protective factors, while the other two signaling axes played a crucial role in promoting the progression of prostate cancer." (PMID 39882449, 2024).
melanoma (234 papers, 2003 to 2025). A malignant, usually aggressive tumor composed of atypical, neoplastic melanocytes. "Tnfsf10 expression has been shown to positively correlate with overall survival, recurrence-free survival and immunotherapy response of patients with melanoma." (PMID 39056192, 2024). "NRIR, firstly found to be associated with melanoma by our study, was positively correlated with CYLD, MLKL, STAT1, and TNFSF10." (PMID 37147395, 2023). "Experiments (in vivo and in vitro) revealed that TNFSF10 was a melanoma metastasis-related gene, which may lie the foundation of the development of novel, molecularly targeted drugs." (PMID 37670976, 2023). "Besides this, apoptosis and cell death were inferred due to the enriched “ER stress” and “Apo-2L (TNFSF10)-induced apoptosis in melanoma” pathways." (PMID 36052162, 2022). "An increased production of the TRAIL-ligand TNFSF10 along with a decrease of the decoy receptor TNFRSF10c suggest that additional factors to DR5 could contribute to the improved apoptosis susceptibility of FKBP51-targeted melanoma cells." (PMID 34589486, 2021). "BCL10 (3.84-fold), TRADD (2.71-fold), CYCS (2.51-fold), DIABLO (2.43-fold), BAD (2.36-fold), BID (2.17-fold), TNFSF8 (2.13-fold), TNFSF10 (2.11-fold), BAX (2.03-fold), and FAS (2.01-fold) were also proapoptotic genes highly upregulated in response to UA treatment in A-375 melanoma cells." (PMID 39473730, 2024).
lung carcinoma (205 papers, 2009 to 2025). "COPD, an inflammatory respiratory disorder that related to inferior prognosis of lung cancer, has been identified that its pathogenesis is affected by tumor necrosis factor-related apoptosis-inducing ligand (TRAIL), which is known as tumor necrosis factor superfamily member 10 (TNFSF10)." (PMID 29581827, 2018).
pancreatic cancer (173 papers, 2003 to 2025). "Notably, among these genes, SOD2, P4HB, and TNFSF10 were identified as hub genes associated with adverse prognostic outcomes in pancreatic cancer." (PMID 38685045, 2024). "Moreover, luteolin diminishes the levels of miR-301-3p that targets caspase-8, ultimately sensitizing pancreatic cancer cells to the TNF superfamily member 10 (TNFSF10, also known as TNF-related apoptosis-inducing ligand (TRAIL))." (PMID 33066509, 2020). "We established and validated a prognostic model for pancreatic cancer with 7 signatures, including ADH1C, APOE, RAP1GAP, NPC1L1, P4HB, SOD2, and TNFSF10." (PMID 38685045, 2024).
hepatocellular carcinoma (168 papers, 2003 to 2025). A malignant tumor that arises from hepatocytes. "Lastly, DNMT2 targets the pro-apoptotic gene TNFSF10 (TRAIL), promoting the proliferation of hepatocellular carcinoma cells." (PMID 41256854, 2025). "SNP in tumor suppressor genes, such as TNFSF10 and TNFSF9, are identified with the pathogenesis of various cancers, such as ovarian cancer and hepatocellular carcinoma, but these polymorphic genes may be answerable for the development of BRCA." (PMID 31311202, 2019).
viral infection (95 papers, 2006 to 2025). "Moreover, the death receptor of TNFSF10 contributes to immune surveillance against viral infection by promoting apoptosis." (PMID 34920753, 2021). "In contrast, virus infection induced expression of those eRNAs as well as the TNFSF10 gene (right)." (PMID 30352805, 2018). "TNFSF10’s (TRAIL) recognized role in apoptosis further highlights the importance of cell death regulation in the context of AKI and viral infections, though its specific contributions require additional exploration." (PMID 39027131, 2024). "Notably, CD4+ T-cells in severe patients showed lower expression of the TNF superfamily ligands TNFSF10 (TRAIL) and TNFSF14 (LIGHT) and the surface protein SLAMF1 and KLRB1, all of which have roles in viral infections." (PMID 33178221, 2020). "As a result, we hypothesized that JUN, VEGFA, TNFSF10, and TLR4 in PBMC can also regulate virus infection of HCC patients." (PMID 31531018, 2019).
ovarian carcinoma (92 papers, 2005 to 2025). A malignant neoplasm originating from the surface ovarian epithelium. "Moreover, patients with high TNFSF10 expression usually exhibited a good response to chemotherapy, while TNFRSF4 was associated with chemosensitivity and good prognosis in ovarian cancer patients, and IRF7 was upregulated in patients in the chemotherapy responsive group." (PMID 36590751, 2022). "For the following genes, we found no significant changes in expression in fibroblasts after treatment with exosomes from ovarian cancer cells: HTATIP2 (HIV-1 Tat interactive protein 2, 30 kDa), IL1B, TGFB1 and TNFSF10 (TRAIL, Tumor necrosis factor (ligand) superfamily, member 10)." (PMID 36012171, 2022).
leukemia (91 papers, 2005 to 2025). A malignant (clonal) hematologic disorder, involving hematopoietic stem cells and characterized by the presence of primitive or atypical myeloid or lymphoid cells in the bone marrow and the blood. "Amongst the re-expressed genes were CDKN2A, EIF2AK2, TNFSF10 and XAFI, all of which are associated with cell cycle inhibition or induction of cell death through increasing caspase activity and the reduction of which are known to be associated with the development of leukemia." (PMID 28881658, 2017). "Tumor necrosis factor (TNF)-related apoptosis-inducing ligand-TNFSF10 (TRAIL), a death receptor ligand, is down-regulated in BCR-ABL1-positive leukemia." (PMID 27233483, 2016). "Some of these AM genes are known to be dysregulated in leukaemia: up regulation of BIRC3 and down regulation of APAF1, CIDEB, FAS, TNFRSF25, TNFSF10 were previously identified by our group as specific alterations of AM genes in leukemic cells." (PMID 20642818, 2010).
gastric cancer (75 papers, 2010 to 2025). A primary or metastatic malignant neoplasm involving the stomach. "The data revealed a gene expression pattern in EBV-positive gastric cancer, highlighting immune response, inflammation, and cell proliferation genes (e.g., GBP4, ICAM1, IL32, TNFSF10)." (PMID 40110195, 2025).
neuroblastoma (56 papers, 2003 to 2026). Neuroblastoma (NB) is the most common solid, extracranial childhood tumor. "The most highly mutated genes, such as MYC, TERT, FASLG, RIPK1, TNFSF10, TARDBP, and CDKN2A, have been well characterized in liver cancer, diffuse large B-cell lymphoma, neuroblastoma, and kidney renal clear cell carcinoma." (PMID 35875102, 2022).
liver cancer (49 papers, 2011 to 2026). An epithelial or non-epithelial malignant neoplasm that arises from the liver. "When DNMT2 is absent, FTO expression increases, leading to a decrease in the m6A methylation level of TNFSF10, which in turn upregulates TNFSF10 expression and significantly inhibits the proliferation and metastasis of DNMT2-deficient liver cancer cells." (PMID 41501031, 2026). "We identified YWHAE as significantly associated with liver fibrosis, AVIL, FIS1, MUC1, ACOT7, CLUH, HNF4A, and TNFSF10 with liver cancer, and AVIL with liver disease-related mortality (FDR-adjusted P values < 0.05)." (PMID 38862964, 2024).
diabetes (45 papers, 2010 to 2025). "Interestingly, we found that deletion of Tnfsf10 in Tregs did not significantly alter diabetes incidence or insulitis in female or male mice, although there was a slight trend toward reduced diabetes incidence." (PMID 33483333, 2021).
bladder cancer (43 papers, 2009 to 2025). "LncRNA XIST and TNFSF10 were highly expressed and miR-129-5p was low expressed (P < 0.05) in bladder cancer cell line." (PMID 38446257, 2024). "Hence, the study revealed a novel regulatory mechanism of lncRNA XIST to promote bladder cancer progression through modulating miR-129-5p /TNFSF10 axis." (PMID 38446257, 2024). "All those results further demonstrated that lncRNA XIST could sponge miR-129-5p to regulate TNFSF10 expression in bladder cancer through these binding sites." (PMID 38446257, 2024). "Mechanistically, lncRNA XIST could sponge miR-129-5p to regulate TNFSF10 expression in bladder cancer." (PMID 38446257, 2024). "Based on this, lncRNA XIST could sponge miR-129-5p to modulate TNFSF10 expression in bladder cancer through the predicted binding site in terms of the mechanism." (PMID 38446257, 2024). "Furthermore, compared with adjacent tissues, lncRNA XIST and miR-129-5p were lowly expressed (P < 0.01) in bladder cancer tissues, and TNFSF10 was highly expressed (P < 0.001)." (PMID 38446257, 2024).